EVI5L (ecotropic viral integration site 5 like)
Description:
Functions as a GTPase-activating protein (GAP) with a broad specificity.
Tractability: PROTAC: ubiquitination databases record sites on it; its protein half-life has been measured.
Gene: Protein-coding gene on chromosome 19 (7,830,182 to 7,864,980, forward strand). Ensembl gene ENSG00000142459.
Subcellular location (Human Protein Atlas): Nucleoplasm; Cytosol; Golgi apparatus
Gene Ontology:
Molecular function: GTPase activator activity; protein binding; small GTPase binding
Biological process: negative regulation of cilium assembly; positive regulation of GTPase activity
Genetic constraint (gnomAD): Loss-of-function variants: 30 observed, 77.84 expected, observed/expected ratio (o/e) 0.39, 90% interval 0.29 to 0.52. The synonymous counts are far from expectation, so gnomAD's model fits this gene poorly and the ratio says little. Missense variants: 809 observed, 951.89 expected, observed/expected ratio (o/e) 0.85, 90% interval 0.8 to 0.9. Synonymous variants: 489 observed, 411.59 expected, observed/expected ratio (o/e) 1.19, 90% interval 1.1 to 1.28.
Homologues: Orthologues: chimpanzee EVI5L (100% identical), guinea pig EVI5L (98% identical), mouse Evi5l (98% identical), rat Evi5l (97% identical), pig EVI5L (97% identical), dog EVI5L (96% identical), rabbit EVI5L (92% identical), zebrafish evi5l (73% identical), tropical clawed frog evi5l (73% identical), macaque EVI5L (65% identical). Paralogues in human: EVI5 (70% identical), RABGAP1 (17% identical), TBC1D10B (17% identical), RABGAP1L (17% identical), TBC1D1 (17% identical), TBC1D4 (17% identical), TBC1D9B (17% identical), USP6NL (16% identical), TBC1D8 (16% identical), TBC1D9 (16% identical), TBC1D10A (15% identical), TBC1D8B (15% identical), and 33 more.
Diseases named in the same sentence as EVI5L in open-access papers:
EVI5L is named in the same sentence as 3 diseases in open-access papers, as found by Europe PMC text mining. Sharing a sentence is not in itself a finding about the gene and the disease. The quoted sentences say what the papers report.
multiple sclerosis (1 paper, 2023). A progressive autoimmune disorder affecting the central nervous system resulting in demyelination. "Multiple sclerosis is a fairly common autoimmune demyelinating disease; EVI5L may therefore play an important role in cellular immunity as an immune-related gene." (PMID 36635413, 2023).
schizophrenia (1 paper, 2017). A major psychotic disorder characterized by abnormalities in the perception or expression of reality. "Based on our analysis for the S-TOGET trio data, three genes in this region, including EVI5L, PRR36, and LYPLA2P2, were detected to be associated with schizophrenia at the suggestive significance level of 5 × 10−5." (PMID 29066733, 2017). "Three genes on chromosome 19p13.2, including EVI5L (ecotropic viral integration site 5 like), PRR36 (proline rich 36), and LYPLA2P2 (lysophospholipase II pseudogene 2), were detected to be associated with schizophrenia at the suggestive significance level of 5 × 10−5." (PMID 29066733, 2017).
tumour (1 paper, 2023). "In addition, we found seven other genes recurrently affected by HBV integration in tumour tissue samples: ECE1, EVI5L, KIF13B, MTX1P1, PLXND1, TECR and USP24." (PMID 37400627, 2023).